IGF1 (insulin like growth factor 1)
Diseases named in the same sentence as IGF1 in open-access papers (continued):
Sharing a sentence is not in itself a finding about the gene and the disease.
cancer (continued). "With regard to cancer mortality, in contrast, a potential reason for the positive association between adult height and cancer mortality is explained by levels of insulin-like growth factor-1 (IGF-1), which are related to the promotion of cell proliferation and inhibition of apoptosis." (PMID 29758048, 2018). "Height may be relevant to cancer risk as a marker for lifetime growth-factor levels (e.g. IGF-1) and/or early-life exposures (socio-economic/environmental/nutritional)." (PMID 29555990, 2018). "Elevated levels of IGF-1 may contribute to cancer risk by inhibiting apoptosis, stimulating cell proliferation and synthesis of sex steroids and inhibiting the synthesis of steroid hormone binding globulin." (PMID 29080978, 2018). "Moreover, high-level detection of plasmatic IGF-1 has been associated with cancer risk and cancer prognosis." (PMID 29721213, 2018). "Several IGF1 SNPs have been reported to be associated with cancer susceptibility." (PMID 30111277, 2018). "Further studies of cancer progression in mice deficient for IGF1 suggest that these mechanisms of tumor growth may be applicable to colon and pancreatic cancers." (PMID 30567377, 2018). "Specifically, a large quantity of data points to the role of mTOR activation in cancer development through protein-induced IGF-1 signaling and to the beneficial effects of caloric and protein restriction not only on aging-associated diseases such as cancer but also on life span." (PMID 30363988, 2018). "Other reports have also indicated that IGF-1 plays an important role in tumor progression and may be a predictor of cancer risk." (PMID 29255466, 2017). "Insulin-like growth factor (IGF) signaling system which consisted of ligands (IGF-1 and IGF-2), growth factor receptors (IGF-1R, IGF-2R) and IGF binding proteins (IGFBPs 1-6), also has been implicated in the development, maintenance, and progression of cancer." (PMID 28460483, 2017). "Moreover, the candidate cancer driver mutations in Ezh2 and Hras were highly enriched in X10 and IGF1 tumors." (PMID 28173837, 2017). "The IGF signaling contains a dynamic network of proteins including ligands (insulin, IGF-1, IGF-2), their associated receptors (IGF-1R and IGF-2R) and several IGF binding proteins (IGFBPs) that participate in the regulation of human cancer development." (PMID 29162853, 2017). "One mechanism by which IGF-1 may raise risk in younger women is by increasing breast density in pre-menopausal women, a known risk factor for cancer." (PMID 28865460, 2017). "Other reports have also indicated that the IGF-1 signaling pathway may be implicated in several cancers." (PMID 29255466, 2017). "The reduction of serum IGF-1 levels could be associated to an impaired hepatic function and patient’s nutritional status, which in the case of cancer patients involves weight loss." (PMID 26808421, 2016). "Cancer associated fibroblasts and TAMs also secrete IGF-1 and promote tumor progression." (PMID 27683110, 2016). "The notion that low IGF‐1 action may be protective from some diseases, such as cancer, but predispose to others, is particularly relevant to older humans, where somatopause leads to age‐related declines in GH/IGF‐1." (PMID 26534869, 2016). "Moreover, low IGF‐1 action is relevant to humans because of its link to less cancer risk, an observation that spurred the development of IGF‐1R antagonists as a clinical cancer treatment." (PMID 26534869, 2016). "Congenital deficiencies in IGF-1 protects against the development of cancer." (PMID 27875990, 2016). "In addition correlative population based studies have suggested a link between circulating serum IGF1 levels risk of cancer development for numerous cancer types." (PMID 27532210, 2016).
cancer (continued). "Nonetheless, when this information is considered relative to the effects of obesity on cancer characteristics at the time of diagnosis, there are many inconsistencies; e.g., a direct effect of IGF-1 on premenopausal cancer versus the inverse association commonly reported." (PMID 27338371, 2016). "Given the role of IGF1 in cancer development and progression, reduced levels of IGF1 because of the rs5742714 genotype may decrease cancer susceptibility and inhibit progression, which may explain our findings in the case-control study." (PMID 27976731, 2016). "However, while low peripheral IGF‐1 is linked to less cancer, it is associated with increased risk for other age‐related diseases in humans." (PMID 26534869, 2016). "The fate of such millions of DNA damaged cells is determined every hour, and even a modest influence of higher IGF-1 level on survival probability might lead to an association of circulating level with cancer risk." (PMID 25866791, 2015). "Yet the connection between circulating IGF-1 levels and cancer risk remains inadequately hidden." (PMID 25866791, 2015). "Two contradictory hypotheses on relationship between IGF-1 and cancer risk are underlined by Pollak." (PMID 25866791, 2015). "These profiles were involved in biological processes such as gluconeogenesis (GO:0006094), G-protein coupled receptor binding (GO:0001664) and phosphorylation (GO:0016310), which have all been shown to be an important part of the IGF-1 signalling cascade in association with cancer." (PMID 26313144, 2015). "High levels of IGF-1 increases the risk of cancer and aggressiveness of malignancies." (PMID 25963193, 2015). "Interestingly, fasting and low protein intake can reduce serum IGF1 levels, and can also reduce tumor growth in animals and cancer risk in some human populations." (PMID 26682276, 2015). "Thus, high levels of IGF1 are associated with increased incidence of cancer progression, while lower levels of IGF1 are associated with decreased incidence of cancer progression in mice and humans." (PMID 25699021, 2015). "Secondly, the influence of IGF-1 level on cancer risk is somewhat related to early carcinogenesis." (PMID 25866791, 2015). "The reduced risk of age-related diseases, particularly cancer is associated with CR which could therefore be related to the reduced IGF-1." (PMID 26061745, 2015). "In contrast, Laron-type dwarfism is associated with low IGF1 levels and reduced cancer risk." (PMID 25699021, 2015). "Dysregulation of the IGF-1 signaling pathway has been implicated in a variety of aging-related diseases including muscle disease, cardiovascular diseases (CVDs), neurodegenerative diseases, metabolic diseases, and cancer." (PMID 25628647, 2014). "Aspects involving IGF-1 deficiency and protection from cancer are also briefly described." (PMID 25333772, 2014). "Since both insulin and IGF1 pathways share cognate receptors, insufficient insulin action may cause dysregulation of the IGF1-SREBP-HMGCR-mevalonate-Ras pathway to increase cancer risk." (PMID 24886453, 2014). "We believe that the effects of fiber intake on IGF system levels and corresponding cancer risk deserve further study.To our knowledge, our study is the first to explore the combined- influence of IGF-1 rs1520220/IGFBP-3 rs2854744 and dietary factors on IGF component levels." (PMID 25285521, 2014). "Indeed, IGF-1 is a potent stimulator of cell growth and proliferation and has been associated with increased risk of several types of cancers in animals and humans." (PMID 24618355, 2014). "Results from in vivo carcinogenesis models and epidemiological studies indicate that high levels of circulating IGF-1 are associated with increased risk and progression of several common cancers, including breast, prostate, colorectal, and ovarian cancer among others." (PMID 25285521, 2014). "To date, however, the results were inconsistent in terms of whether 19-repeat allele increases IGF-1 levels or cancer risks." (PMID 23530598, 2013).
cancer (continued). "The risk of cancer has been found to be higher among people with raised concentrations of IGF-1." (PMID 23431471, 2013). "Furthermore, numerous studies have linked alterations in IGF-1 with resistance to cytotoxic agents and indeed inhibitors of these pathways have been developed for target cancer therapy." (PMID 22852056, 2012). "High insulin levels and the associated changes of the IGF-1 axis may be associated with cancer development." (PMID 22778714, 2012). "The increased number of type 2 DM patients with cancer after age 60 years is partly due to loss of the estrogen protection effect of menopause; in addition, insulin-like growth factor 1 (IGF-1) may play a role." (PMID 22701471, 2012). "It has been reported that high blood levels of IGF-1, existing years before the detection of malignancy, can predict an increase in risk for prostate, breast, colorectal and lung cancers." (PMID 22418926, 2012). "The plasma or serum level of IGF-1 was found to be associated with an increased risk of cancer." (PMID 22839452, 2012). "Zinc status may influence IGF-1 signaling, which may in turn affect not only systemic growth, but cancer risk." (PMID 22852056, 2012). "Accordingly, two possible strategies might be used to reduce IGF-related cancer risk, namely a reduction in IGF-1 blood levels and interference with IGF-1 activity in the cancer cell." (PMID 22418926, 2012). "Elevated circulating IGF-1 is an established risk factor for many cancer types." (PMID 23050968, 2012). "In contrast, plant-based dietary regimens are associated with reduced intake of insulinotropic and IGF-1 elevating amino acids as well as cow ́s milk-derived estrogens and in contrast increase the uptake of potential cancer-preventive natural mTORC1 inhibitors." (PMID 22891897, 2012). "They provide circumstantial evidence that increased IGF-1 levels are associated with cancer." (PMID 21696633, 2011). "Epidemiology studies also indicate that IGF-1 is involved in the risk of cancer development." (PMID 21729319, 2011). "The emerging belief that higher levels of IGFBP3 may decrease mammographic density and may decrease the risk of cancer through low IGF1/IGFBP3 ratio must be further substantiated." (PMID 20302654, 2010). "These authors report that the positive relationship between leg length and risk for these cancers may be due to the effects of insulin-like growth factor 1 (IGF-1)." (PMID 20617018, 2010). "A person with high levels of IGF-1 may be predisposed to cancer and his/her risk of developing cancer would increase with the presence of other such factors." (PMID 17953765, 2007). "Besides polymorphic variation in the IGFBP3 gene, another strong predictor of variability in IGFBP-3 levels was the same IGF1 haplotype that was associated, in the same direction, with cancer risk." (PMID 16404426, 2006). "Polymorphisms of the IGF1 gene and of genes encoding for the major IGF-I carriers may predict circulating levels of IGF-I and have an impact on cancer risk." (PMID 16404426, 2006). "The insulin-like growth factor (IGF-1) signalling is highly implicated in cancer." (PMID 15956962, 2005). "Lower IGF-1 levels shift cells into a more quiescent state, reducing unnecessary proliferation, thereby lowering the risk of accumulating mutations that could lead to cancer." (PMID 39940361, 2025). "However, elevated IGF-1 activity has also been linked to increased cancer risk and reduced lifespan, suggesting that while it supports tissue maintenance, excessive or dysregulated IGF-1 signalling may negatively impact healthy ageing." (PMID 41010500, 2025). "However, excessive protein intake, particularly from animal sources, has been linked to elevated levels of insulin-like growth factor-1, which may promote tumor growth and progression in certain cancers, such as prostate and colorectal cancer." (PMID 40428567, 2025).
cancer (continued). "Reduced inflammation: Prolonged fasting and FMD can reduce levels of circulating IGF-1 (insulin-like growth factor-1), a hormone linked to cancer risk, and promote a switch to a state that reduces inflammation, which can potentially decrease the chances of cancer development and progression." (PMID 38321992, 2024). "We observed differential mRNA expression of growth factors and cytokines (TGFβ, IL-6, and IGF1) both in BMSCs and, subsequently, in cancer-associated fibroblasts (CAFs), which might represent the main cell subpopulation responsible for inflammatory homeostasis in MM, among the two patient subgroups." (PMID 39609411, 2024). "Interestingly, IGF1 is related, in a ligand-independent manner, to the activation of the androgen receptor, which might be implicated in cancer progression." (PMID 37373068, 2023). "Therefore, it is hypothesized that genetic variation affecting the IGF1/insulin axis may also influence cancer risk, progression and therapy response." (PMID 38136416, 2023). "Another hypothesis is that other metabolic mechanisms, such as increased synthesis and biological activity of insulin-like-growth-factor (IGF)-1, have been postulated to link animal-protein-rich diets to increased anabolic activity and to cause the development of cancer cells." (PMID 36771499, 2023). "While the mechanisms responsible for cancer protection in LS are yet to be identified, the interpretation of epidemiological data is consistent with the notion that homozygous congenital IGF1 deficiency might confer protection against future development of cancer." (PMID 35626664, 2022). "Furthermore, IGF-1 signaling is potentially associated with cancer progression." (PMID 36498723, 2022). "A prevalent hypothesis has proposed that exercise may reduce the risk of cancer through an exercise-dependent regulation of common cancer risk factors, including sex hormones, insulin, insulin-like growth factor-1, and pro-inflammatory cytokines, which are all associated with obesity and adiposity." (PMID 35361802, 2022). "It has been shown that IGF-1 is an important factor in the development of breast cancer in pre-menopausal women, and therefore lycopene’s reduction in this growth factor may reduce the risk of this cancer." (PMID 35205105, 2022). "Thus, any indirect effect that IGF‐1 may have on cancer risk through modulating a global aging pathway might be overshadowed by its direct, cancer‐promoting effects." (PMID 34363732, 2021). "Since cancer is a leading cause of death worldwide, and the low efficacy of many existing therapies is a major clinical challenge, it is essential to understand the prognostic and immunological impact of IGF-1 and IGF-1R among cancer types comprehensively in order to develop novel immunotherapies." (PMID 34804946, 2021). "Therefore, KCC3, KCC4, EGF, and IGF-1 may be a panel of promising diagnostic biomarkers to predict cancer patient outcomes." (PMID 35008759, 2021). "Furthermore, IGF1 deficiency in untreated LS is thought to decrease the incidence of cancer." (PMID 33434161, 2021). "Since cancer-associated soluble factors such as inflammatory cytokines and IGF-1, or nutrition deprivation increased the plasma levels of DCN, the upregulation of DCN could reflect the chronic inflammation or metabolic dysfunction observed with cancer progression at least partially." (PMID 34884232, 2021). "Insulin-like growth factor 1 receptor (IGF1R) gene expressed by cancer cells was highly associated with estrogen response signatures in BC, which may demonstrate that the binding effect of IGF1 on IGF1R as well as activating estrogen signaling enhanced cancer growth." (PMID 34676217, 2021). "Notably, IGF-1 circulating level are positively associated with an increased risk of colorectal and prostate cancers, as well as with premenopausal breast cancer, although the strength of these associations varies by cancer site." (PMID 34205356, 2021).
cancer (continued). "Difficulties in designing potential isoform IGF1 agents arise due to the complexity of IGF1 gene splicing and the presence of different factors associated with post-translational modifications, as well as bioactivity of IGF1 and its isoforms in physiology and pathology (including cancer)." (PMID 32977489, 2020). "Interestingly, rs2162679 of IGF1 had been reported to be associated with several kinds of cancer, in which the allele G could also decrease the risk of cancer onset." (PMID 32025377, 2020). "Importantly, these changes also run counter to theoretical concerns that increased GH/IGF-1 signaling may exacerbate cancer risk, which have been raised in some contexts." (PMID 32701508, 2020). "Therefore, this study aimed to investigate the sex-specific associations between height and 24 site-specific cancers and to assess whether the association differed by IGF-1." (PMID 32921791, 2020). "For example, genome studies of the longest-lived bat Myotis brandtii showed that cancer resistance might be attributed to growth suppression by specific mutations in the growth hormone receptor that may reduce the GH-insulin-like growth factor 1 signalling pathway." (PMID 31249297, 2019). "Previous studies have shown that, among antihyperglycemic medication, insulin and sulfonylurea may increase the risk of cancer by interacting with insulin and insulin like growth factor 1 (IGF-1) receptor signalling, which enhances proliferation and carcinogenesis." (PMID 31518336, 2019). "The links between dietary carbohydrates and cancer risk are hypothesized to involve mechanisms that directly implicate players in insulin-mediated pathways across various tissue types as well as through modulation of IGF-1 bioactivity." (PMID 30895469, 2019). "Physical activity may mediate numerous pathways associated with cancer progression and the development of other chronic diseases including energy metabolism, insulin, insulin-like growth factor-1, chronic inflammation, the immune system, and antioxidant pathways." (PMID 29385194, 2018). "In addition, insulin and IGF-1 have been implicated to play a role in cancer." (PMID 28768896, 2017). "However, states of relative IGF-1 deficiency seem to be protective against cancer." (PMID 28954393, 2017). "Decrease the activity of the IGF-1 axis could be a desirable target for reducing cancer risk, but it is also well known that the activation of the IGF-1/AKT/mTOR (insulin-like growth factor-1/protein kinase B/mammalian target of rapamycin) pathway is one of the keys for muscular growth." (PMID 27737674, 2016). "When considered along with upregulated signaling pathways downstream of IGF1 and leptin, and increased proliferative markers and body weight in irradiated mice, our results are suggestive of increased risk for metabolic alterations and cancer in GI tract after energetic heavy ion radiation exposure." (PMID 27558773, 2016). "However, it is currently unknown if IGF1/IGF1-receptor biology also influences cancer frequency between large and small breeds, although it is tempting to speculate that cancer frequency may be linked to genetic determinants of size." (PMID 26056371, 2015). "Therefore, these diseases might generate a potential link to increased cancer risk due to the IGF-1 induction of AGR2." (PMID 25956506, 2015). "In mouse, TRPV2 is activated by IGF-1, a cytokine endowed with potent mitogenic and anti-apoptotic effects on cancer cells; moreover, increased proliferation and survival of human bladder smooth muscle cells, induced by mechanical stress, is associated with increased IGF-1 levels." (PMID 24709905, 2014).